SLIT2 (slit guidance ligand 2)
Diseases named in the same sentence as SLIT2 in open-access papers (continued):
Sharing a sentence is not in itself a finding about the gene and the disease.
osteoporosis (1 paper, 2025). A condition of reduced bone mass, with decreased cortical thickness and a decrease in the number and size of the trabeculae of cancellous bone (but normal chemical composition), resulting in increased fracture incidence. "Using both aging-induced and ovariectomy-induced osteoporosis models in wild-type and Slit2-transgenic mice, we demonstrate that Slit2 overexpression markedly mitigates bone loss and preserves trabecular architecture." (PMID 40937144, 2025). "Furthermore, Slit2-Tg mice exhibited significantly lower bone loss in both aging-induced and ovariectomy-induced osteoporosis models." (PMID 40937144, 2025). "This study provides novel insights into the therapeutic potential of Slit2 as a target for osteoporosis treatment." (PMID 40937144, 2025). "H&E staining revealed that Slit2 plays a critical role in maintaining bone homeostasis in the OVX-induced osteoporosis model." (PMID 40937144, 2025). "In this study, we established an aging-induced osteoporosis model using wild-type (WT) and Slit2-transgenic (Slit2-Tg) mice, as well as an estrogen-deficient ovariectomy-induced osteoporosis model." (PMID 40937144, 2025). "To investigate the bone quality of Slit2-Tg mice compared to WT mice in age-related osteoporosis, we established an age-related osteoporosis model using Slit2-Tg and WT mice." (PMID 40937144, 2025). "In this study, Micro-CT and H&E staining analyses revealed that the femoral microarchitecture in both aging-induced and ovariectomy-induced osteoporosis models of Slit2-Tg mice were significantly superior to that of WT mice." (PMID 40937144, 2025). "In this study, we demonstrated that Slit2-Tg mice exhibit superior femur bone properties compared to WT controls in both aging and ovariectomy-induced osteoporosis models." (PMID 40937144, 2025). "Future studies using Slit2 knockout models or exogenous recombinant Slit2 protein supplementation will help clarify its full therapeutic potential in osteoporosis." (PMID 40937144, 2025). "Collectively, these findings highlight Slit2 as a promising therapeutic target for osteoporosis." (PMID 40937144, 2025). "These consistent findings across different age groups and osteoporosis models suggest that Slit2 plays a critical role in bone metabolism regulation and may have broad applicability in osteoporosis pathogenesis." (PMID 40937144, 2025). "Our findings suggest that elevated Slit2 levels in bone tissue may exert a protective effect against osteoporosis progression, providing valuable insights into the potential of Slit2 as a therapeutic target for osteoporosis." (PMID 40937144, 2025). "To further validate the role of Slit2 in other types of osteoporosis, we established ovariectomy (OVX)-induced osteoporosis models using 8-week-old WT and Slit2-Tg mice." (PMID 40937144, 2025). "However, the relationship between Slit2 and Src, and the PI3K/AKT pathway, during osteoporosis requires further investigation." (PMID 40937144, 2025).
ovarian tumour (1 paper, 2011). "Recent studies have implied that SLIT2 can inhibit the invasion of endometrial and ovarian tumour cell lines." (PMID 22132142, 2011).
Papillary thyroid cancers (1 paper, 2022). "Papillary thyroid cancers patients with negative SLIT2 expression have significantly increased risk of recurrence and metastasis." (PMID 35053460, 2022).
peripheral nerve injury (1 paper, 2019). Injury to a peripheral nerve. "Previous studies on Slit focusing on SCs suggested that peripheral nerve injury could lead to the expression of various neurotrophic factors in SCs, including NGF, BDNF, neurotrophin 4/5, insulin growth factor 1 and 2, and Slit2 and Slit3." (PMID 31607866, 2019).
pneumothorax (1 paper, 2019). Abnormal presence of air in the pleural cavity. "In the present study, 40.7% of the pneumothorax lung specimens expressed greater or equal amounts of Slit2-ΔE15 when compared with Slit2-WT." (PMID 30717252, 2019).
pregnancy (1 paper, 2023). The status during which female mammals carry their developing young (EMBRYOS or FETUSES) in utero before birth, beginning from FERTILIZATION to BIRTH. "Another study revealed that SLIT2 is expressed in extravillous trophoblasts (EVTs) of tubal pregnancy, and that changes in SLIT2 expression are linked to vascular remodeling of the fallopian tube." (PMID 36793891, 2023).
pulmonary diseases (1 paper, 2021). "Specifically, ROBO2 is involved in the signal transduction of SLIT2, which has been shown to have an important function in pulmonary diseases." (PMID 34442380, 2021).
pulmonary fibrosis (1 paper, 2021). Chronic progressive interstitial lung disorder characterized by the replacement of the lung tissue by connective tissue, leading to progressive dyspnea, respiratory failure, or right heart failure. "SLIT2 and ROBO2 have been evidenced to prevent fibrotic processes in several diseases, including pulmonary fibrosis." (PMID 34442380, 2021).
R5 (1 paper, 2013). "In addition, our results are aligned with a recent study demonstrating that the N-terminal fragment of the Slit2 protein inhibits X4 and R5 viral infection by binding to the Robo1 receptor and antagonizing the HIV gp120-mediated Rac1-LIMK-cofilin pathway for actin rearrangement." (PMID 23782904, 2013).
renal agenesis (1 paper, 2023). Renal agenesis (RA) is a form of renal tract malformation characterized by the complete absence of development of one or both kidneys (unilateral RA or bilateral RA respectively), accompanied by absent ureter(s). "Moreover, The SLIT2 variant identified in Fetus 8 may relate to the unilateral renal agenesis observed during fetal evaluation." (PMID 36478354, 2023).
tauopathy (1 paper, 2025). Neurodegenerative disorders involving deposition of abnormal tau protein isoforms (tau proteins) in neurons and glial cells in the brain. "Elevated SLIT2 levels were associated with demyelination in tauopathy mouse model and human AD brains." (PMID 41331787, 2025). "Dap12 deletion suppressed Slit2 upregulation and mitigated demyelination, while lentiviral-Slit2 overexpression induced myelin loss in tauopathy mice." (PMID 41331787, 2025). "Our study identifies a novel DAP12-dependent mechanistic link between upregulated Slit2 expression in excitatory neurons and oligodendrocyte-dependent myelination loss in tauopathy." (PMID 41331787, 2025). "Notably, we identified a DAP12-dependent mechanistic link between upregulated Slit2 expression in EN and oligodendrocyte-dependent myelination loss in tauopathy." (PMID 41331787, 2025). "Further analysis confirmed that Slit2-Robo1 signaling was selectively elevated from EN to OLs in tauopathy mice." (PMID 41331787, 2025). "Our study implicates SLIT2 as a candidate neuronal cue that modulates oligodendrocyte function and myelin integrity in the tauopathy brain." (PMID 41331787, 2025). "Lentiviral Slit2 was unilaterally administered into the hippocampus of 3-4-month-old female tauopathy mice." (PMID 41331787, 2025). "In summary, our study uncovers a novel mechanistic link between microglial DAP12 signaling, neuronal SLIT2 expression, and oligodendrocyte dysfunction in the context of tauopathy." (PMID 41331787, 2025). "Taken together, our results support a model in which DAP12-dependent Slit2 upregulation in tauopathy may recapitulate its developmental roles, ultimately leading to impaired myelination and contributing to neurodegeneration." (PMID 41331787, 2025). "To assess whether Slit2 upregulation leads to demyelination, we overexpressed mouse Slit2 in female tauopathy mice using our previously established protocol." (PMID 41331787, 2025). "Our results showed that SLIT2, a secreted signaling protein that acts extracellularly through ROBO receptors, is significantly increased in MBP-positive neurites in tauopathy brain." (PMID 41331787, 2025). "Co-immunostaining of SLIT2 and MBP revealed increased SLIT2 expression in neurites and its colocalization with MBP-positive axons in tauopathy mice, which was markedly attenuated by Dap12 deletion." (PMID 41331787, 2025).
tumor (168 papers, 2004 to 2025). "The Slit2/Robo signaling pathway has been implicated in both tumor suppressing and tumor-promoting roles, depending on the tumor type." (PMID 41227302, 2025). "Tumor-promoting gene transcription alterations were also caused by Slit2 as seen by CEBPβ1 and Stat6 phosphorylation, which induce macrophage polarization towards a tumorigenic phenotype." (PMID 39456164, 2024). "In control (CTRL) tumors, CD45+CD11b+F4/80+Ly6G–TAMs (tumor-associated macrophages) made up approximately 12% of all cells; in Slit2-knockdown tumors, this number was just 6%." (PMID 39456164, 2024). "Downregulation of the tumor suppressive angiocrine factor Slit2 and upregulation of its inhibitor receptor EphA2 on tumor-associated ECs promote tumor proliferation and motility." (PMID 38426109, 2024). "Slit2 treatment further induced gene expression associated with a tumor-promoting macrophage phenotype by activating MMP-9, VEGF-a, Mrc1, Ccl19, TGF-β1, IL-10, Cd209a, and Arg1." (PMID 39456164, 2024). "We also analyzed if reduced tumor growth observed in Robo1 knockout and Slit2‐treated SBC xenografts is linked to reduced angiogenesis." (PMID 35838343, 2023). "SLIT in the SLIT-ROBO signaling axis can regulate cell motility mediating behaviors associated with tumor aggressiveness by regulating actin and the microtubule cytoskeleton.Tumor growth can be inhibited by inhibiting SLIT2 signaling." (PMID 37700840, 2023). "In vitro and in vivo experiments revealed that ROBO1 suppresses the proliferation and angiogenesis of CCA, while E280* nonsense mutation of ROBO1 loses the tumor-suppressing effects through interruption of the SLIT2/ROBO1 signaling pathway." (PMID 35615148, 2022). "Recurrent variants (p.R119Q and p.R131C of ROBO1 and p.R462C, p.A340T, p.P322L, p.R461C, p.R388W, p.R420W, and p.G576R of SLIT2) found that implies the pathogenic significance of the variants across tumour types." (PMID 33318575, 2020). "The underlying mechanism that Slit2 regulates tumor development and progression is very complicated." (PMID 27923383, 2016). "In summary, our data revealed that the downregulation of srGAP1 in CRC tissues is associated with tumor progression and poor prognosis, and srGAP1-Cdc42 regulatory axis is a key downstream target of Slit2-Robo1 pathway in CRC." (PMID 27923383, 2016). "In liver tissues, differential expression of ROBO1, ROBO4 and SLIT2 was found to be associated with clinicopathological parameters such as tumor staging and differentiation." (PMID 19114000, 2008). "We compared the results of SLIT2 methylation status in our tumour series to the previously reported results for allelic loss of 1p or 3p loss, N-myc amplification and 17q gain." (PMID 14735202, 2004). "In addition, low Slit2 expression is associated with a better prognosis because it can inhibit macrophages, improve tumor vascular function, and enhance sensitivity to chemotherapy and immunotherapy." (PMID 40149733, 2025). "Furthermore, low Slit2 expression was associated with better prognosis as it inhibited macrophages, improved tumor vessel function and increased the sensitivity to chemotherapy and immunotherapy." (PMID 39456164, 2024). "In addition, SLIT2 treatment enhances M1‐like phagocytic macrophages and reduces M2‐like tumor‐associated macrophages (TAMs) in SCLC tumors." (PMID 35838343, 2023). "Such SLIT-mediated communications between cancer and endothelial or stromal cells may regulate metastasis, because endothelial Slit2 deficiency suppresses metastasis, whereas Slit2 deficiency in tumor cells promotes metastasis." (PMID 36942388, 2023). "Moreover, selective deletion of SLIT2 in tumor cells in a murine tumor model caused increased tumor metastatic potential." (PMID 33672863, 2021). "SLIT2 is aberrantly expressed in various cancers and plays a role in the regulation of cancer cell apoptosis, cancer metastasis, tumor-associated inflammation, and tumor progression." (PMID 32760720, 2020).
tumor (continued). "All SLIT2 methylated tumours contained unmethylated SLIT2 alleles that might be attributable to the presence of contaminating normal tissue (tumour samples were not microdissected)." (PMID 14735202, 2004). "However, SLIT2 hypermethylation was significantly associated with tumor recurrence." (PMID 35053460, 2022). "This suggests SLIT2 may be implicated as a tumour suppressor in colorectal carcinogenesis." (PMID 23671423, 2013). "SLIT2 is typically a tumor suppressor, where its silencing via promoter hypermethylation in cancer cells is a common mechanism to promote tumor progression by allowing increased migration, invasion, and metastasis." (PMID 40362385, 2025). "In highly metastatic BC, the axon guidance molecule slit guidance ligand 2 (SLIT2) in the tumor vasculature drives increased innervation." (PMID 41415714, 2025). "N-acetylcysteine (NAC) modulates the tumor microenvironment by regulating the population of cancer-associated fibroblasts and inducing the activation of various cytokines, including CXCL12, SLIT2, and DCN." (PMID 40001479, 2025). "The miR‐218 co‐expression and co‐regulation with its host gene SLIT2/3 have been shown mainly in tumor cells and motor neurons." (PMID 40873389, 2025). "The promoting effect of Slit2 on malignant tumors can be caused by the activation of PI3K-γ, further inducing microglia/macrophage chemotaxis and tumor-supportive polarization." (PMID 40149733, 2025). "In the context of cancer, the role of SLIT proteins (particularly SLIT2) is predominantly tumor suppressive." (PMID 40362385, 2025). "This SLIT2, secreted by surrounding fibroblasts, suppresses the tumor by inhibiting the PI3K/Akt/β-catenin pathway via the Robo1 receptor." (PMID 40508075, 2025). "SLIT2 slows growth, while ROBO1 promotes it, by regulating the TGF-β1/GSK3-β/β-catenin signaling pathway in tumor cells and tumor-associated macrophages (TAMs)." (PMID 41217667, 2025). "Mechanistically, SLIT2 promotes microglia/macrophage chemotaxis and tumor‐supportive polarization via roundabout guidance receptor 1/2 (ROBO1/2)‐mediated PI3Kγ activation in macrophages." (PMID 40843131, 2025). "Day 21 Slit2-knockdown tumors had fewer F4/80+ myeloid cells than day 18 Slit2-overexpressing tumors or day 21 controls, according to immunofluorescence examination of tumor sections." (PMID 39456164, 2024). "The secretion of Slit2 by tumor cells attracts Robo1 present in endothelial cells to migrate towards the tumor, inducing new blood vessel formation." (PMID 39456164, 2024). "As the main source of various cell movement and adhesion-related proteins, SCs promote the migration of SCs to cancer cells and release chemical molecules to facilitate tumor proliferation in PDAC with low expression of SLIT2." (PMID 38081962, 2024). "The contribution of Slit2 to malignancy was attributed to the activation of PI3K-γ that further led to microglia/macrophage chemotaxis as well as tumor-supportive polarization." (PMID 39456164, 2024). "When comparing Slit2-knockdown to control tumors, a lower expression of the immunosuppressive PD-L1, PD-L2, and IL-6 was noted in tumor cells." (PMID 39456164, 2024). "Endothelial cells downregulate Slit2, a tumor-suppressive angiocrine factor inhibited by ephrin 2 (Eph2), facilitating tumor cell proliferation and motility." (PMID 39325128, 2024). "Overexpression of SLIT2 and deletion of ROBO1 in SCLC cells have shown the anti-tumor and pro-tumor effects of SLIT2 and ROBO1, respectively, through macrophage polarization." (PMID 38983267, 2024). "In the context of tumors, SLIT2 possesses a proangiogenic role, and elevates tumor cell aggressiveness and migration, metastatic spread, and resistance to therapeutics." (PMID 38275876, 2024). "In precancerous intestinal lesions and during tumor progression, Slit2/Robo1 signaling triggers the Wnt/β-catenin pathway by down-regulating E-cadherin and induces EMT." (PMID 38081962, 2024).
tumor (continued). "Slit2 tumor‐suppressor activity acts primarily through Robo1, as the treatment of Robo1−/− SCLC with rSlit2 protein, does not further inhibit the tumorigenic properties of these cells." (PMID 35838343, 2023). "Here the authors show that hepatoctyes overexpress SLIT2 to enable premetastatic niche formation for ROBO1-positive PDAC cells to support the survival of these tumour cells in the liver." (PMID 36792623, 2023). "Tumour cells expressing full-length ROBO1 protein (Kpc1199Robo1-FL or Panc02Robo1-FL) were intrasplenically implanted into Slit2 fl/fl (CTRL), CKO and CKO-RE mice." (PMID 36792623, 2023). "Here, we show that Slit2 expression levels are reduced in SCLC tumors relative to the adjacent normal lung in three independent tumor cohorts." (PMID 35838343, 2023). "Endothelial-derived SLIT2 binds to the ROBO1 receptor in tumor cells and initiates cancer cell migration to endothelial cells and blood vessels." (PMID 37015905, 2023). "Molecular analysis showed that ROBO1 knockout or SLIT2 overexpression suppresses the transforming growth factor beta 1 (TGF‐β1)/β‐catenin signaling pathway in both tumor cells and macrophages." (PMID 35838343, 2023). "In the CKO-RE group, the paracrine resumption of SLIT2 expression by hepatocytes restored the outgrowth ability of Robo1-FL-expressing tumour cells." (PMID 36792623, 2023). "Mechanistic studies showed that the Slit2/Robo1 signaling prevents the polarization of pro‐tumor M2‐like macrophages in the tumor microenvironment (TME) by targeting Tgf‐β1 signaling." (PMID 35838343, 2023). "Overall, our data show that Slit2 suppresses the GSK3/β‐catenin signaling pathway in the tumor cells and macrophages to inhibit SCLC growth." (PMID 35838343, 2023). "Specifically, inhibition of the WNT/β-catenin pathway by Slit2/Robo signaling enhances the formation of β-catenin and E-cadherin complexes, increasing tumor cell adhesion and inhibiting tumor invasion and migration, thereby improving patient prognosis." (PMID 37834436, 2023). "In summary, our results for the first time, establish a tumor‐suppressive role of Slit2 and tumor‐promoting role of Robo1 in SCLC." (PMID 35838343, 2023). "Using genetically engineered SCLC cells, adenovirus gene therapy, and preclinical xenograft models, we show that SLIT2 overexpression or the deletion of ROBO1 restricts tumor growth in vitro and in vivo." (PMID 35838343, 2023). "Although Slit2 has been identified as a tumor suppressor in several malignancies, its role in regulating the tumor microenvironment and immune infiltrates is undefined." (PMID 35838343, 2023). "SLIT2 is also a known tumor suppressor and negatively regulates primary tumor growth in many types of cancers." (PMID 37311584, 2023). "We find that Slit2 can suppress Tgf‐β1‐induced polarization of macrophages towards pro‐tumor M2‐like macrophages by suppressing β‐catenin levels." (PMID 35838343, 2023). "In 27 of the 29 (93.1%) patients with tumor SLIT2 hypermethylation, SLIT2 was also aberrantly methylated in ctDNA samples." (PMID 38169730, 2023). "In agreement with our data from SCLC tumor cells, Slit2‐treated BMDMs showed translocation of β‐catenin outside of the nucleus." (PMID 35838343, 2023). "Molecular analysis showed that SLIT2 overexpression or ROBO1 deletion suppresses the transforming growth factor‐beta 1 (TGF‐β1)/β‐catenin signaling pathway in both tumor cells and macrophages." (PMID 35838343, 2023). "Flow cytometry analysis of macrophages phagocytosed tumor cells revealed that the Slit2‐treated tumors harbor a significantly increased number of phagocytic macrophages." (PMID 35838343, 2023). "Our work showed that Slit2 does inhibit SCLC tumor growth, cell migration, and local invasion in vitro and in vivo." (PMID 35838343, 2023). "Consistently, overexpression of SLIT2 in CAPAN-1 cells derived from human PDAC liver metastases with a high level of ROBO1 expression increased the tumour burden." (PMID 36792623, 2023).